STAT3 (signal transducer and activator of transcription 3)
Diseases named in the same sentence as STAT3 in open-access papers (continued):
Sharing a sentence is not in itself a finding about the gene and the disease.
tumor (continued). "Moreover, mutations in STAT3 and STAT6 are known to increase PD-L1 expression and enhance the production of tumor-associated antigens." (PMID 40243506, 2025). "The TME promotes tumour progression by creating an immunosuppressive environment that hampers the body’s antitumour immune response, primarily through the Nuclear Factor Kappa B (NF-κB) and Signal Transducer and Activator of Transcription 3 (STAT3) pathways." (PMID 40407951, 2025). "This relationship highlights the relevance of STAT3 and IL-6 as potential therapeutic targets, suggesting that strategies aimed at modulating this pathway could be promising for combating tumor progression." (PMID 40733498, 2025). "Notably, IL-1β can induce IL-6 production, a cytokine known to promote tumor progression via STAT3 activation." (PMID 41445736, 2025). "STAT3 inhibition can promote apoptosis in cancer cells and prevent tumor growth, but it may also enhance the aggressiveness of HCC tumors by increasing the expression of EMT‐related proteins." (PMID 41409896, 2025). "Moreover, STAT3 activation promotes an immunosuppressive tumor microenvironment by enhancing the infiltration of myeloid-derived suppressor cells and M2 macrophages, inhibiting dendritic cell maturation, and recruiting Tregs." (PMID 40949156, 2025). "In NSCLC, activation of the JAK2/STAT3 pathway promotes tumor progression." (PMID 39840666, 2025). "STAT3’s role in promoting cell proliferation, inhibiting apoptosis, and modulating the immune response makes it central to oncogenesis and tumor progression, particularly in cancers where STAT3 activation correlates with poor prognosis, treatment resistance, and increased metastasis." (PMID 40075607, 2025). "Additionally, IL-1RA disrupts the senescence-associated secretory phenotype of tumors, protecting proliferating tumor cells from senescence regulation in a paracrine manner; IL-10 enhances distant metastasis by activating the c-Met/STAT3 signaling pathway." (PMID 40528159, 2025). "Although the molecular mechanism remains largely unknown, Adriamycin-induced paradoxical tumor growth and drug resistance may be led by persistent STAT3 activity." (PMID 40696387, 2025). "This includes confirming the regulation of STAT3 by Sestrins across various tumour contexts, defining the transcriptional interplay between Sestrins and Nrf2 in oncogenic settings, and clarifying the mechanisms by which Sestrins interact with mTORC2 and activate AKT signalling in cancer." (PMID 40361504, 2025). "Consequently, the inhibition of STAT3 expression can further inhibit the binding of PD‐1 to PD‐L1, thereby preventing tumor immune escape." (PMID 40364727, 2025). "However, our data from a mouse transplantable tumor model indicate that targeting STAT3 only in neutrophils (NStat3−/− mice) is sufficient to achieve a significant reduction in tumor growth." (PMID 40885734, 2025). "Sustained STAT3 activation leads to the proliferation of many tumor cells.The widespread expression of IL-21R in immune enables IL-21 to activate macrophage, DCs, NK cells, B cells, NK T cells, CD4+T cells, CD8+ T cells, Treg cells, Th17 cells, follicular helper T cells, etc.." (PMID 40469178, 2025). "DLBCL-derived IL-8 interacted with its receptor (CXCR2) on neutrophils, resulting in the formation of NETs, which directly increased the expression of Toll-like receptor 9 (TLR9) pathways in DLBCL and subsequently activated the NFκB, STAT3 and p38 pathways, promoting tumor progression." (PMID 41019086, 2025). "Moreover, it was shown that treating DU145 and A2058 tumor cells with a STAT3 inhibitor led to a reduction in HIF-1α." (PMID 40408503, 2025). "They showed that tumor-derived exosomes promote the production of pro-inflammatory mediators, where NF-κB activation leads to IL-6 production, a prerequisite for subsequent STAT3 activation in an autocrine or paracrine way." (PMID 40443670, 2025).
tumor (continued). "By modulating signaling pathways such as NF-κB and STAT3, specific miRNAs can influence the balance between pro-inflammatory M1 and anti-inflammatory M2 macrophage phenotypes, thereby affecting both the inflammatory response and anti-tumor immunity." (PMID 40109347, 2025). "ENSA K63 lactylation upregulates STAT3/CCL2 signaling in tumor cells." (PMID 39883522, 2025). "Beyond inhibiting tumor cell migration through the suppression of the STAT3 signaling pathway, SLC9A2 may exert additional biological functions that contribute to the inhibition of CRC cell metastasis." (PMID 40474298, 2025). "Furthermore, IL-8 (CXCL8) can further upregulate MMP1 expression by activating the STAT3 signaling pathway, thereby enhancing tumor cell invasiveness." (PMID 40809844, 2025). "Additionally, B7-H3 induces epithelial–mesenchymal transition (EMT) in tumor cells through the JAK2/STAT3 pathway, thereby increasing their invasive and metastatic potential." (PMID 41463642, 2025). "Besides, increased expression with cyclin proteins between S and G2/M phases of the cell cycle and the interaction with STAT3 nuclear translocation are most likely to indicate the regulatory role of ProT in promoting tumor development." (PMID 40259641, 2025). "Furthermore, STAT3 activation promotes the development of new blood vessels, encouraging tumor growth and metastasis." (PMID 40881676, 2025). "In addition, STAT3 contributes to tumor cell invasion by upregulating matrix-degrading enzymes such as MMP-2 and MMP-9." (PMID 40723906, 2025). "This accumulating evidence suggests the pro-tumor function of STAT3 activation in neutrophils." (PMID 40358184, 2025). "Emerging evidence highlights that STAT3 hyperactivation occurs not only in tumor cells but also in immune cells infiltrating the tumor microenvironment (TME), affecting a broad spectrum of immune populations, including macrophages, T cells, NK cells, and dendritic cells." (PMID 40704145, 2025). "Additionally, ibuprofen impairs key transcription factors NFκB and STAT3, leading to reduced adaptation to hypoxic stress, decreased tumor cell viability, and migration." (PMID 40408503, 2025). "Intracellular PD-L1 was shown to promote tumor cell survival by inhibiting STAT3-dependent apoptosis, and ongoing work will investigate whether similar pathways are active within PD-L1-blocked TAMs." (PMID 41050935, 2025). "Furthermore, in vivo results showed that the NLP-EXOSOME COMPLEX STAT3 silencer significantly prolonged the survival of tumor-bearing mice, with a remarkable reduction in tumor size observed by MRI analysis." (PMID 40427146, 2025). "Multiple lines of transcriptomic evidence in tumor-educated THP1 cells point to STAT3 pathway activation, including upregulation of canonical STAT3 targets (SOCS3, CISH, BCL3, JUNB, PIM1) and increased expression of STAT3-activating ligands (IL6, IL11, LIF, OSM) in response to TNBC contact." (PMID 41514627, 2025). "Previous studies have primarily focused on the in vitro and in vivo biological activities of carnosol, such as its ability to inhibit tumor growth by modulating key signaling pathways, including nuclear factor kappa B (NF-κB) and signal transducer and activator of transcription 3 (STAT3)." (PMID 40006508, 2025). "In tumors, chemokines not only direct the migration of immune cells to influence the anti-tumor immune response but also regulate the proliferation, invasion, metastasis, and angiogenesis of tumor cells by activating diverse signaling pathways such as STAT3 and NF-κB." (PMID 39915476, 2025). "The STAT3 inhibitor W1131 has demonstrated anti-tumor effects by inducing ferroptosis and may synergize with chemotherapy to further suppress tumor growth." (PMID 41293165, 2025). "Napabucasin is a first‐in‐class tumor stemness inhibitor that targets STAT3." (PMID 41346572, 2025).
tumor (continued). "Notably, when inflammatory and immune cells infiltrate tumors, the communication between tumor cells and their microenvironment is predominantly influenced by the activation of STAT3 and its interaction with NF-κB." (PMID 40420174, 2025). "The IL6/JAK/STAT3 signaling axis is aberrantly activated in a wide range of tumors, and the transduction of this signaling axis promotes tumor cell invasion of surrounding tissues, resistance to drugs, and suppression of anti‐tumor immunity." (PMID 40874680, 2025). "Additionally, IL-10/JAK1/STAT3 pathway activation induces vasculogenic mimicry, forming vasculogenic mimicry that support tumor blood supply." (PMID 41479912, 2025). "One study employing a cRGD (cyclic arginine-glycine-aspartate)/RBCM (erythrocyte membrane) dual-headed nanocarrier platform co-delivering gemcitabine and silencing CTRP6 expression demonstrated that this strategy amplified ferroptosis in tumor cells via the NRF2/STAT3 signaling pathway." (PMID 41228203, 2025). "Importantly, aberrantly activated STAT3 can mediate communication between cancer cells and their immunological microenvironment, leading to tumor-induced immunosuppression." (PMID 41453852, 2025). "The STAT3 pathway is known to play a key role in immune regulation and tumor suppression." (PMID 40076725, 2025). "Interestingly, our results from in vivo blocking assays using 4-IPP, MIF inhibitor and stattic, p-STAT3 inhibitor clearly demonstrated that sizes of tumor from the 4-IPP and stattic injection groups are significantly reduced compared to the control group." (PMID 39891284, 2025). "In our study, STAT3 expression was measured in tumor cells, suggesting that the observed decrease may reflect complex interactions between tumor cells and microglia." (PMID 40805225, 2025). "Despite the presence of divergent data regarding the sporadic ineffectiveness of the suppression of STAT3 activity, it is imperative to acknowledge that strategies that disrupt STAT3 signalling can nevertheless elicit substantial antitumour effects by modulating the tumour microenvironment." (PMID 40729003, 2025). "Further, in vitro studies revealed an anti-inflammatory and pro-tumour effect of STAT3 ASO." (PMID 40428391, 2025). "Furthermore, ODZ10117, another SH2 domain inhibitor, has been shown to prevent tyrosine phosphorylation and STAT3 dimer formation, ultimately reducing tumor progression." (PMID 40166646, 2025). "Blocking the expression of STAT3, the phosphorylated form of which is detected in approximately 70% of cancers, results in the inhibition of tumour cell proliferation in in vitro assays and the inhibition of tumour progression in vivo." (PMID 40003568, 2025). "F. nucleatum can induce EMT and tumor cell stemness via the IL-6/STAT3 signaling pathway." (PMID 41597595, 2025). "Several studies have illustrated that blocking STAT3 or 5 signaling leads to tumor cell apoptosis." (PMID 40003884, 2025). "Additionally, knocking out the STAT3 pathway has been shown to increase the proliferation of cytotoxic NK cells, thereby enhancing their tumor-killing capacity." (PMID 39859231, 2025). "Overall, these data suggest that tumor stem cells activate OX40 transcription via STAT3 in ECs." (PMID 40026246, 2025). "Interestingly, in a larger proportion of tumors (69%), the immune cells of the tumor microenvironment expressed the STAT3 protein." (PMID 40426911, 2025). "Importantly, aberrant STAT3 signalling through pathways such as VEGFA not only drives tumour growth but also contributes to drug resistance by promoting a tumour-supportive microenvironment, enhancing cancer cell survival, and impairing therapeutic efficacy." (PMID 40407951, 2025). "In sum, our results show how RBM14 overexpression promotes STING activation in the context of DNA damage, and how this effect impairs immunosuppressive STAT3 signaling and may enhance NK cell-mediated tumor recognition and killing." (PMID 39870664, 2025).
tumor (continued). "Moreover, distinct OVs engage specific cell death pathways: HSV (endoplasmic reticulum stress), Ads (mitochondrial apoptosis via caspase-3/9), and Newcastle disease virus (NDV, regulated by STAT3)—each enhancing tumor-killing." (PMID 41314288, 2025). "STAT3 is usually considered an oncogene but may act as a tumor suppressor under specific circumstances." (PMID 40433378, 2025). "Together, these data substantiate the hypothesis that FPHPE exerts anti‐inflammatory and anti‐tumor effects through targeted inhibition of the JAK2/STAT3 signaling cascade, reinforcing its potential as a dual‐action therapeutic agent in HCC management." (PMID 41200213, 2025). "Finally, several studies have now identified a crosstalk between tumor intrinsic PD-L1 functions and IFN signaling that control STAT3/Caspase 7 pathways and tumor cell DNA damage response —all of which can regulate protein production with extrinsic functions." (PMID 39663510, 2025). "In GBM, TAMs directly sustain tumor stemness via the TGF-β1/integrin αvβ5/Src/STAT3 pathway." (PMID 41417432, 2025). "Strategies aimed at restoring miR-10a-5p levels or targeting the miR-10a-5p/TFR1/STAT3 axis could potentially enhance anti-tumor immune responses and improve treatment outcomes in HCC patients." (PMID 41551164, 2025). "Additionally, in vivo experiments demonstrated that Prkci knockout in colorectal cancer cells reduced tumor growth, angiogenesis, and Jak2/Stat3 activation, significantly extending survival in a mouse model." (PMID 40840329, 2025). "In addition to its role in angiogenesis, SLC9A2 also suppresses tumor cell metastasis and invasion by downregulating the STAT3 signaling pathway, thereby promoting the EMT process in CRC." (PMID 40474298, 2025). "Moreover, treated macrophages with STAT3 inhibitor also effectively blocked M2 polarization induced by ENH‐overexpressing tumor cells." (PMID 40536254, 2025). "Pharmacologic inhibition of STAT3 or VEGF-A suppressed tumor growth in BM-bearing mice." (PMID 41436606, 2025). "Additionally, ITGA2 has been confirmed to increase the proliferation and metastatic potential of various tumor cells by activating the STAT3 signaling pathway." (PMID 40940943, 2025). "Therefore, the addition of fedratinib makes sense because STAT3 plays an important role in the tumor microenvironment." (PMID 39400496, 2025). "The expression of p-STAT3 was increased in tumor tissues from HCC cells overexpressing SNX17." (PMID 40303303, 2025). "Similarly, IL-6 binding to its receptor on tumor cells activates the Janus Kinase-Signal Transducer and Activator of Transcription 3 (JAK-STAT3) pathway, promoting cell proliferation, survival, and angiogenesis, all of which contribute to chemoresistance." (PMID 40404908, 2025). "Reduced VEGF expression from impaired STAT3 activity may inhibit angiogenesis, limiting blood and nutrient supply, ultimately affecting tumor growth and metastasis." (PMID 40118821, 2025). "Also, we unveiled that myeloid cells transdifferentiation was mediated by tumor cell-secreted MIF through the JAK/STAT3 signaling pathway." (PMID 39891284, 2025). "Mice were treated with JAK2 and STAT3 inhibitors to assess immune and tumor responses." (PMID 40384867, 2025). "To elucidate the epigenetic mechanisms by which acetylated STAT3 modulates tumor-suppressor gene expression in TNBC, we hypothesized that this modification might enhance CpG island methylation, thereby downregulating the expression of such genes." (PMID 40083697, 2025). "This epigenetic modification represses anti‐tumor genes while activating IL‐6/STAT3 signaling." (PMID 40904700, 2025).
tumor (continued). "Importantly, overexpression of STAT3 in tumor tissue has been found to be correlated with poor prognosis in HCC patients." (PMID 40303303, 2025). "In various tumor models, these STAT3 degraders significantly inhibited tumor progression, particularly demonstrating significant synergistic effects in immune checkpoint therapy‐resistant models, showing promising safety profiles and clinical translation potential." (PMID 41049269, 2025). "Interestingly, the MIF secreted by tumor cells is a key factor to induce the transdifferentiation of myeloid cells into apCAFs through the JAK/STAT3 signaling pathway." (PMID 39891284, 2025). "Since MDA-MB-231 xenografts with knockdown of HMGN5 exhibited reduced tumor growth, this suggests that the interaction between STAT3 and HMGN5 could be used as a future target for treatment." (PMID 40507264, 2025). "In addition, HDAC7 and SIRT5 can also reduce STAT3 acetylation levels, promoting tumour apoptosis, whereas CBP and KAT6B, as acetyltransferases, can reverse this process." (PMID 39778006, 2025). "STAT3 activation facilitates the growth and persistence of tumor cells during SCC carcinogenesis." (PMID 40399946, 2025). "STAT3 is a well-documented oncogenic factor that is highly expressed across numerous tumor types." (PMID 40906092, 2025). "Furthermore, we found that both AhR and c‐MYC inhibition in tumor cells increased level of STAT3 phosphorylation, which was required for I3A‐induced immunogenicity." (PMID 40583248, 2025). "Notably, STAT3 expression correlated significantly with immune modulation, particularly through suppressed NK cell activity—a key anti-tumor mechanism—potentially facilitating immune evasion via impaired IFN-γ and TNF-α production." (PMID 40636126, 2025). "IHC staining analysis revealed that sesamin treatment significantly reduced the expression of STAT3 in xenograft tumor tissues, indicating that the inhibitory effect of sesamin on STAT3 expression is consistently validated in both in vitro and in vivo experiments." (PMID 40303286, 2025). "Furthermore, the activation of STAT3/MMP-9 signaling furthers tumor progression and dissemination by enhancing extracellular matrix degradation." (PMID 41294803, 2025). "Furthermore, STAM2 significantly influences the expression of MMP2/MMP9, as well as the phosphorylation of JAK2/STAT3 in cancer cells, thereby enhancing tumor malignancy." (PMID 40149859, 2025). "STAT3 signaling exhibits a strong correlation with tumor growth and progression." (PMID 40275278, 2025). "Similarly, high STAT3, JAK, Bcl-2, and PCNA expression in musculoskeletal tumors intensifies JAK/STAT3 signaling activation, accelerating tumor growth, inhibiting apoptosis, and promoting angiogenesis." (PMID 40420174, 2025). "Previous studies have shown that STAT3 is closely related to tumor immunity." (PMID 40918170, 2025). "TGF-β can influence behavior of tumor by modulating NF-κB and STAT3." (PMID 40535567, 2025). "For evaluating possible impacts of the secretome of the hAMSCs on tumor growth plus progress via EGFR/c-Src/IRSp53/p-AKT/p-Stat3/cyclin D1 signaling pathway, first coculturing of HT-29 colon cancerous cells /hAMSCs was fulfilled for 72 h afterward, they underwent MTT assay." (PMID 41200137, 2025). "STAT3 activation can occur independently of IL-6 targeting, as it lies downstream to other cytokines including IL-10, IL-22, and IL-27, which are broadly pro-tumor in nature and found in abundance in KM-LUAD." (PMID 40356899, 2025). "STAT3, in turn, promotes tumor growth by regulating genes involved in angiogenesis." (PMID 41041322, 2025). "Finally, B7-H3 has been implicated in fostering an immunosuppressive tumor microenvironment by increasing the production of IL-10 and TGF-β through the stimulation of the p-JAK2/STAT3 signaling pathway in vivo." (PMID 40801642, 2025). "First, IL-6 promotes tumor cell proliferation through STAT3 activation." (PMID 41244903, 2025).